G3BP1 (G3BP stress granule assembly factor 1)
Diseases named in the same sentence as G3BP1 in open-access papers (continued):
Sharing a sentence is not in itself a finding about the gene and the disease.
tumor (continued). "G3BP1 has been found to be involved in the regulation of multiple cellular functions, and it promotes RCC tumor progression, metastasis and induce EMT transition through the IL-6/G3BP1/STAT3 signaling axis in RCC." (PMID 40546967, 2025). "In pancreatic cancer, G3BP1 binds to BART mRNA, promoting its downregulation, and enhancing tumor cell invasion and metastasis." (PMID 41191214, 2025). "The results demonstrated that EEF2, G3BP1, G3BP2, PRPF8, RECQL4, STOML2, and UBB exhibited significantly higher expression levels in the majority of tumor tissues, whereas METTL3 and NR2C2 showed a widespread downregulation trend." (PMID 41341921, 2025). "The upregulation and the tumor-promoting function of G3BP1 in NPC were reported recently, but the factors increasing the level of G3BP1 in NPC remain elusive." (PMID 39510185, 2024). "We also evaluated the protein expression levels of G3BP1 in UALCAN database, showing that G3BP1 was significantly higher expression in primary tumor tissues." (PMID 34967276, 2022). "IHC analysis of de novo tumours derived from KRASG12D-transduced human mammary cells showed increased levels of stress-related translational targets of YB-1, including HIF1α, NRF2, G3BP1 and membranous CAIX, compared to matching normal tissue." (PMID 34294889, 2022). "We also found a higher expression of YTHDF3 and G3BP1 in highly resistant CRPC and specific NEPC tissues, consistent with prior studies reporting higher levels of G3BP1 and YTHDF3 in different tumor tissues, and are negatively prognostic." (PMID 34939643, 2022). "Previous studies showed that G3BP1 participated in the epithelial-mesenchymal transition process via modulating Wnt/β-catenin, Smad, and STAT3 signaling to promote tumor progression and metastasis." (PMID 33726799, 2021). "We conducted immunohistochemical (IHC) staining using antibodies against G3BP1 and G3BP2 with the paired lung sections derived from the tumor (bottom) and non-tumor regions (top)." (PMID 34521423, 2021). "The tumor suppressor gene PTEN acts on the phosphoinositide 3-kinase (PI3K) pathway and inhibits the expression of G3BP1 through its own phosphatase activity, thereby also inhibiting tumorigenesis." (PMID 34526993, 2021). "Collectively, these results indicated that G3BP1 contributes to promoting RCC cell proliferative, migratory, and invasive capacities, thereby facilitating the transitioning of tumor mesenchymal phenotype." (PMID 29717134, 2018). "The results showed that a significant (p < 0.01) reduction of primary RCC tumor size was observed in mice with G3BP1 knockdown as compared to the scramble control group, suggesting G3BP1 plays an important role in RCC tumor growth in vivo." (PMID 29717134, 2018). "The results revealed that treatment of IL-6 (100 ng/ml) significantly (p < 0.01) promoted tumor cell migration and invasion in RCC ACHN cells, while G3BP1 depletion strongly attenuated the IL-6-induced enhancement of RCC cell migration and invasion." (PMID 29717134, 2018). "In this study, we showed that the knockdown of G3BP1 dramatically impaired EGF-induced RCC cell chemotaxis, an essential component of tumor dissemination during progression and metastasis, indicating EGF-mediated chemotaxis in RCC is probably via G3BP1." (PMID 29717134, 2018). "Besides, xenografted tumor growth in nude mice were also performed using HepG2 cells that overexpress UTXWT, UTXTPR, or UTXD336G in G3BP1 knockout background at 4 days after cell injection." (PMID 40536321, 2025). "In summary, YBX1 promotes tumor progression through its transcription factor activity, exerting its effects via various downstream targets such as MUC1, CDC25a, NANOG, Kindlin-2, G3BP1, AURKA, SPP1, the EGFR-RAS-MAPK axis, CORO1C, among others, depending on the specific tumor type." (PMID 40799245, 2025).
tumor (continued). "In the brain metastasis model, we observed that the tumor size was larger in the G3BP1 overexpression group than in the stattic injection group, and no clear tumor was found in the control group." (PMID 38164170, 2024). "G3BP1, a key component protein of SGs, binds to specific RNA molecules through its C-terminal RNA recognition motif (RRM) to regulate the stability of mRNA and affect the proliferation of tumor cell." (PMID 37179344, 2023). "G3BP1, EIF2AK2, TRIM25, and ACTA1 were among the top-ranked proteins, and these were closely related to tumor proliferation, metastasis, and invasion, suggesting that seRNA-NPCM may play a crucial role in NPC tumorigenesis and development." (PMID 37479693, 2023). "We detected the expression of G3BP1 in nude mouse tumors by immunohistochemical staining and confirmed that the efficiency of G3BP1 down-expression was not restored during tumor growth." (PMID 36330442, 2022). "The m5C-related factors form a tumor microenvironment suitable for migration and metastasis of various cancer cells by regulating some known tumor promoters, such as HDGF, TGF-β, FGF2, and G3BP1." (PMID 35464855, 2022). "Some regulators functioned as tumour suppressors, including METTL5, YTHDC2, and G3BP1." (PMID 34802443, 2021). "G3BP1 promotes cell proliferation by inhibiting PMP22 mRNA expression in breast cells and facilitates tumour metastasis and invasion by inhibiting the expression of E-cadherin and by increasing the expression of TGF-β signalling genes, Smad target genes, vimentin, Snail, Slug, fibronectin and ZEB1." (PMID 34044876, 2021). "In addition, downregulated G3BP1 restricts the invasion and migration of MDA-MB-231 cells compared to upregulated G3BP1, facilitating the tumour invasion and migration of MCF-7 cells." (PMID 34044876, 2021). "There is a connection and association between G3BP1 and TAT-RasGAP317-326; however, TAT-RasGAP does not sensitize tumor cells to chemotherapy via G3BP1." (PMID 35004322, 2021). "Using in vitro and in vivo models of senescence and tumor growth, we determined that although G3BP1 does not affect the senescence process, it does play a vital role in the ability of senescent cells to induce the SASP." (PMID 33020468, 2020). "Without G3BP1, senescent cells are unable to promote their paracrine-mediated effects in vitro and unable to promote tumor cell proliferation in vitro and in vivo." (PMID 33020468, 2020). "In addition, IL-6 can induce the expression of G3BP1, while G3BP1 depletion diminishes the IL-6-elicited STAT3 activation and leads to inhibition of tumor cell growth and invasion in RCC." (PMID 29717134, 2018). "Collectively, oncogenic G3BP1 serves as a signaling linkage molecule from upstream IL-6/EGF elicited stimulations to downstream STAT3 signaling, eventually contributing to promote tumor cell growth and metastasis in RCC." (PMID 29717134, 2018). "Moreover, knockdown of G3BP1 suppressed the mesenchymal phenotype of MDA-MB-231 cells in vitro and suppressed tumor growth and lung metastasis of 4T1 cells in vivo." (PMID 25962958, 2015). "This nuclear location was not affected by the RasGAP-derived peptide however, indicating that the mechanism by which TAT-RasGAP317–326 sensitizes tumor cells to genotoxin-induced apoptosis does not rely on modulation of the nuclear G3BP1 content." (PMID 22205990, 2011). "Third, the peptide efficiently sensitizes tumor cells lacking G3BP1 to genotoxin-induced death." (PMID 22205990, 2011). "Furthermore, compared with the control G3BP1‐KO xenografts, neither UTXWT/UTXTPR nor UTXD336G xenografts in G3BP1‐KO background showed significant changes in tumor volumes." (PMID 40536321, 2025).
neurodegenerative disease (5 papers, 2019 to 2026). A disorder of the central nervous system characterized by gradual and progressive loss of neural tissue and neurologic function. "Further analyses will be required in order to elucidate how G3BP1 and G3BP2 regulate protein aggregation in neurodegenerative diseases, including PD." (PMID 31501480, 2019).
lung (3 papers, 2019 to 2025). "Hence, we investigated whether G3BP1+/INS mRNA+ condensates could also be detected in beta cells within snap-frozen surgical specimens of living donors undergoing pancreatectomy for a variety of disorders of the exocrine pancreas." (PMID 40355555, 2025). "The positive percentage of increased expression of G3BP1 and YB1 proteins was 57.5% (69/120) and 61.7% (74/120) in lung SCC, 55.1% (70/127) and 57.5% (73/127) in lung ADC, and 14.6% (7/48) and 12.5% (6/48) in noncancerous control lung tissues, respectively." (PMID 31560169, 2019).
neurodevelopmental disorder (2 papers, 2021). A behavioral and cognitive disorder with onset during the developmental period that involves impaired or aberrant development of intellectual, motor, or social functions. "In addition to G3BP1, searching for other RNA-binding proteins that are present in dendrite and synapses as the downstream targets of PRMT8 would be critical for illuminating the multifaceted functions of PRMT8 in neurodegeneration and neurodevelopmental disorders in the future." (PMID 34833008, 2021).
bacterial infection (1 paper, 2026). "Here, we generated phospho-mimic (G3BP1D) and phospho-dead (G3BP1A) variants and expressed them in Arabidopsis, revealing that the phosphorylation state of G3BP1 affects susceptibility to bacterial infection by influencing ROS production and salicylic acid (SA) accumulation." (PMID 42267125, 2026).
head-neck tumors (1 paper, 2014). "G3BP1 is over-expressed in NETs, which in this respect resemble other tumors such as colon, thyroid, breast, lung, and head-neck tumors." (PMID 25546138, 2014).
myopathy (1 paper, 2020). A disease of the muscle in which the muscle fibers do not function properly. "Cytoplasmic aggregates of the stress granule proteins TIA1 and Ras GTPase-activating protein-binding protein 1 (G3BP1) are observed in muscle biopsy specimen of MATR3-myopathy, suggestive of defects in stress granule formation or dynamics." (PMID 32823799, 2020).
G3BP1 also shares sentences with these, for which no sentence is quoted: atrial fibrillation (3 papers); breast tumor (3); cardiovascular disease (3); cervical cancer (3); lupus nephritis (3); systemic lupus erythematosus (3); acute liver failure (2); autoimmune disease (2); Autoimmunity (2); digestive system tumors (2); esophageal squamous cell carcinoma (2); Parkinson’s (2); rheumatoid arthritis (2); viral diseases (2); Anosmia (1); cardiac ischemia (1); ciliopathies (1); Cirrhosis (1); Crohn disease (1); deep venous thrombosis (1); diabetes (1); enterovirus infection (1); frontotemporal dementia (1); glomerulonephritis (1); influenza (1); intervertebral disc degeneration (1); invasive ductal carcinoma (1); ischemia (1); kidney cancer (1); kidney damage (1).
A further 18 diseases each share a sentence with G3BP1 in 1 paper.